PVT1 (Pvt1 oncogene)
Diseases named in the same sentence as PVT1 in open-access papers (continued):
Sharing a sentence is not in itself a finding about the gene and the disease.
endothelial dysfunction (2 papers, 2022 to 2025). In vascular diseases, endothelial dysfunction is a systemic pathological state of the endothelium (the inner lining of blood vessels) and can be broadly defined as an imbalance between vasodilating and vasoconstricting substances produced by (or acting on) the endothelium. "Thus, all those researches indicated the role of PVT1 involved in diseases is related to angiogenesis and endothelial dysfunction." (PMID 35036445, 2022).
experimental autoimmune encephalomyelitis (2 papers, 2021 to 2022). An autoimmune demyelinating disease of the central nervous system that is produced experimentally in animals by the injection of homogenized brain or spinal cord in Freund's adjuvant. "Interestingly, a previous study verified that PVT1 is also increased in the exosome derived from M2 macrophage in experimental autoimmune encephalomyelitis." (PMID 34514000, 2021).
kidney stone (2 papers, 2021 to 2024). "Moreover, the elevated expression of ceRNAs such as NEAT1, PVT1, hsa-miR-23b-3p, hsa-miR-429, hsa-miR-139-5p, CCL7, and ROBO2, along with the presence of infiltrating immune cells like Mps and mast cells, may be associated with the development of kidney stones." (PMID 38397450, 2024). "The results indicated that significant expressions of ceRNAs (NEAT1, PVT1, hsa-miR23b-3p, hsa-miR-429, hsa-miR-139-5p, CCL7, and ROBO2) and infiltrating immune cells (Mps and mast cells) may be involved in the pathogenesis of kidney stones." (PMID 38397450, 2024).
Lewis lung carcinoma (2 papers, 2019 to 2020). "Then, 1 × 10^6 G-MDSCs transfected with si-Pvt1 mixed with 0.8 × 10^6 Lewis lung carcinoma (LLC) cells were implanted via s.c. injection into WT C57BL/6 mice." (PMID 30925926, 2019). "In this study, we found for the first time that Pvt1 is a target of HIF-1α under hypoxia in G-MDSCs from Lewis lung carcinoma mice." (PMID 30925926, 2019). "To shed light on the potential effect of Pvt1 on G-MDSC activity, we used a murine Lewis lung carcinoma model to investigate the detailed mechanism by which Pvt1 affects G-MDSCs." (PMID 30925926, 2019).
malignant pleural mesothelioma (2 papers, 2016 to 2018). A malignant neoplasm that arises from mesothelial cells in the pleura and shows a diffuse growth pattern. "In this regard, frequent coamplification and cooperation between c-MYC and PVT1 oncogenes have been observed to promote malignant pleural mesothelioma." (PMID 29701689, 2018).
metastatic colorectal cancer (2 papers, 2021 to 2022). "However, the association between single-nucleotide polymorphisms (SNPs) in PVT1 and the chemotherapy response in metastatic colorectal cancer has yet to be clarified." (PMID 35433465, 2022).
metastatic disease (2 papers, 2020 to 2021). "The results revealed that the expression level of PVT1 was higher in metastatic tumors." (PMID 34336125, 2021). "In addition, Zhou and colleagues demonstrated that PVT1 could be enriched by enhancer of zeste homolog 2 (EZH2), a marker of an advanced metastatic disease in numerous types of cancer including ATC, which may also contribute to the regulation of TSHR expression." (PMID 32760219, 2020).
multiple sclerosis (2 papers, 2019 to 2021). A progressive autoimmune disorder affecting the central nervous system resulting in demyelination. "For example, down-regulation of PVT1 correlates with the differentiation of Th17 cells and the duration of multiple sclerosis, a chronic immune-mediated disease." (PMID 31304055, 2019).
pancreas adenocarcinoma (2 papers, 2016 to 2022). "For example, lncRNA Pvt1 oncogene (PVT1) was reported to promote pancreatic adenocarcinoma progression via the miR-20a-5p/ULK1 axis, which is associated with poor prognosis." (PMID 35662010, 2022). "Kaplan-Meier survival analyses revealed that PVT1 overexpression was associated with worse survival rates in KIRC and pancreas adenocarcinoma (PAAD)." (PMID 27366943, 2016).
Prader-Willi syndrome (2 papers, 2013 to 2019). "In addition, several genes encoding exclusively non-coding RNA species, including IPW (Imprinted in Prader-Willi syndrome) and the oncogene PVT1 were expressed as circular isoforms in both mice and humans." (PMID 24039610, 2013).
prostate adenocarcinoma (2 papers, 2020 to 2021). "PVT1 is a long intergenic non-coding RNA (lincRNA) that is overexpressed in twenty-five different tumor tissues including prostate adenocarcinoma." (PMID 33430890, 2021). "Further, within prostate adenocarcinomas of PCAWG cohort, 17 tumors had A/A genotype, only 2 were with A/T and none were with T/T genotype but, similar to the observation in the pan-cancer data, the expression of PCAT1, PVT1, and MYC was found to be higher in those with A/T genotypes." (PMID 32680982, 2020).
rectal cancer (2 papers, 2021 to 2022). A primary or metastatic malignant neoplasm that affects the rectum. "For example, PVT1, which is highly up‐regulated in rectal cancer cells and tissues, functions as a ceRNA in rectal cancer via the PVT1/miR‐30d‐5p/RUNX2 axis to promote cell proliferation and invasion." (PMID 34613665, 2021). "The expression levels of the onco-lncRNAs, including CCAT1, LOC152578, UCA1, CRNDE, PVT1, MALAT1, XLOC_000303, XLOC_006844, BCAR4, and HOTAIR, were significantly increased in the rectal cancer patients compared to the control group." (PMID 35654932, 2022).
retinoblastoma (2 papers, 2020). A malignant tumor that originates in the nuclear layer of the retina. "LncRNAs PVT1, AFAP10AS1, HOTAIR, BANCR, H19, DANCR and LINC00202 were up-regulated in retinoblastoma tissues while MT1JP and BDNF-AS were down-regulated." (PMID 32514246, 2020).
T cell lymphomas (2 papers, 2008 to 2009). "Mouse T-cell lymphomas show retroviral insertions at PVT1 and over-expression of PVT1 and one of PVT1's microRNA products and more retroviral insertions are seen at the PVT1 locus than at the MYC locus." (PMID 19419571, 2009). "In mouse T cell lymphomas induced by retroviral insertions into the locus, the Pvt1 transcripts, and at least one of their microRNA products, mmu-miR-1204 are overexpressed." (PMID 18194563, 2008).
abortion (1 paper, 2020). the ending of pregnancy by removing a fetus or embryo before it can survive outside the uterus. "Long noncoding RNA PVT1 is decreased in villi tissue samples from spontaneous abortion, and PVT1 regulates trophoblast migration." (PMID 33123590, 2020).
allergic rhinitis (1 paper, 2025). Inflammation of the nasal mucous membranes caused by an IgE-mediated response to external allergens. "In allergic rhinitis, PVT1 exacerbates inflammation, resulting in an imbalance between Th1 and Th2 cells." (PMID 40493320, 2025).
aneurysm (1 paper, 2021). Bulging or ballooning in an area of an artery secondary to arterial wall weakening. "Moreover, PVT1, the hub lncRNA in the ceRNA network, was reported to be related to aneurysm." (PMID 33750300, 2021).
Arrhythmia (1 paper, 2025). Any cardiac rhythm other than the normal sinus rhythm. "Elevated expression of lncRNA PVT1 was found to be an independent risk factor for recurrence after RFA in AF patients, suggesting that lncRNAs may serve as noninvasive biomarkers or independent predictors of related arrhythmia events." (PMID 37702834, 2025).
Autoimmunity (1 paper, 2024). The occurrence of an immune reaction against the organism's own cells or tissues. "The lncRNA PVT1 was found to be specific to T cells and studies have shown it to influence metabolic pathways in T cells in the context of autoimmunity, as well as antigen processing and presentation throughout several cancers." (PMID 38396008, 2024).
benign breast disease (1 paper, 2022). "In patients with benign breast disease, BCO40587 expression was positively correlated with BDNF (r = 0.67, P = 0.0003), HOTAIR (r = 0.6, P = 0.0019), CCAT2 (r = 0.52, P = 0.009), and PVT1 (r = 0.42, P = 0.44) expressions." (PMID 36376369, 2022).
benign pancreatic tumour (1 paper, 2016). "And H19, HOTAIR, HOTTIP, MALAT1, and PVT1 levels did not significantly differ between NPT and benign pancreatic tumours (BPT) tissues (p values were 0.522, 0.759, 0.200, 0.631, and 1.000, respectively)." (PMID 27028998, 2016).
bladder tumor (1 paper, 2020). "Meanwhile miR-194-5p was in contrast and miR-194-5p could partially reverse the function of PVT1 in malignant bladder tumor cells." (PMID 33188158, 2020).
Bloom syndrome (1 paper, 2023). Bloom syndrome (BSyn) is a rare chromosomal breakage syndrome characterized by a marked genetic instability associated with pre- and postnatal growth retardation, facial sun-sensitive telangiectatic erythema, increased susceptibility to infections, and predisposition to cancer. "In terms of specific mechanisms, the expression of LncRNA PVT1 upregulated by METTL3-mediated m6A modification on LncRNA PVT1, which subsequently sequestered miR-27b-3p within cells, thereby indirectly promoting the bloom syndrome protein expression." (PMID 37365581, 2023).
cervical tumour (1 paper, 2024). "This allele‐specific activity can be extrapolated to the cervical tumour samples as well, because TAD3189 is the most recurrently integrated TAD among cervical tumours, and we also observed the overexpression of oncogenes MYC and PVT1 within them." (PMID 38013620, 2024).
colorectal adenocarcinoma (1 paper, 2020). The most common type of colorectal carcinoma. "PVT1 fusion genes were first described when amplified allele of MYC in colorectal adenocarcinoma cell line showed displacement of Exon 1 and Intron 1 of MYC by PVT1 resulting in DNA rearrangement." (PMID 32117705, 2020).
COVID-19 (1 paper, 2021). A disease caused by infection with severe acute respiratory syndrome coronavirus 2. "The result obtained for the time points and type of IFN treatment reduced expression of EGOT, GABPB1-AS1, IDI2-AS1, LINC00312, LINC00662, MIAT, PVT1, SNHG7; expression of these lncRNA was increased in SARS-CoV-2 infected cells or in the tissue obtained from COVID-19 patients." (PMID 34940755, 2021). "PVT1 was downregulated in severe COVID-19 patients compared with non-severity." (PMID 34940755, 2021).
dyslipidemia (1 paper, 2022). "When adjusted for EH risk factors, including age, gender, BMI, smoking history, FBG, and dyslipidemia, the significant association between PVT1 rs80177647 was also observed (additive model: TA: OR = 1.768, 95% CI = 1.144-2.731, P = 010; dominant model: OR = 1.723, 95% CI = 1.128-2.631, P = 0.012)." (PMID 35036445, 2022).
fibroma (1 paper, 2021). A non-metastasizing neoplasm arising from the fibrous tissue. "Moreover, we tested PVT1 expression levels in plasma samples from 80 BC patients, 70 fibroma patients, and 70 healthy controls." (PMID 34922601, 2021).
hand fracture (1 paper, 2021). "In the present study, the level of miR-497-5p showed a downward trend over time in both intra-articular and hand fracture patients and the changes reached a significant level at 21 days after treatment, which was in contrast to the serum PVT1 levels." (PMID 34592894, 2021). "It was found that the level of PVT1 increased gradually, while miR-497-5p showed a downward trend over time in both intra-articular and hand fracture patients, and the changes reached a significant level at 21 day after treatment." (PMID 34592894, 2021). "In hand fracture patients, similar expression changes of PVT1 levels were also found." (PMID 34592894, 2021).
hepatoblastoma (1 paper, 2024). Hepatoblastoma (HB) is a malignant hepatic tumor and is the most common pediatric liver cancer. "Mechanistically, PVT1 accelerated the cell cycle progression of HB cells by activating STAT3, and inhibiting STAT3 effectively counteracted PVT1's effects on hepatoblastoma cell cycle progression and proliferation." (PMID 38390281, 2024). "PVT1 was found to promote hepatoblastoma cell proliferation in vitro and in vivo." (PMID 38390281, 2024). "Another study demonstrated that PVT1 exhibited significantly higher expression in 43 human hepatoblastoma tissues compared to adjacent non-tumor tissues." (PMID 38390281, 2024).
Hypercalcemia (1 paper, 2021). An abnormally increased calcium concentration in the blood. "Accordingly, lncRNA score and PVT1 expression were increased with varying degrees of hypercalcemia in PC." (PMID 33910638, 2021). "Further, lncRNA score, but not PVT1 in this study, was more efficient than iPTH in diagnosing PC among patients with hypercalcemia after water ingestion before hospitalization." (PMID 33910638, 2021). "Furthermore, AUCs were calculated only from patients with hypercalcemia at the first fasting state after administration, because lncRNA score and PVT1 were not dysregulated in patients with normal serum calcium after water ingestion." (PMID 33910638, 2021).
intracranial aneurysms (1 paper, 2025). "This study explores the differential expression of lncRNA PVT1 in intracranial aneurysms (IAs) and its role in the phenotypic switching of vascular smooth muscle cells (VSMCs)." (PMID 40289758, 2025).
ischemia (1 paper, 2021). A hypoperfusion of the BLOOD through an organ or tissue caused by a PATHOLOGIC CONSTRICTION or obstruction of its BLOOD VESSELS, or an absence of BLOOD CIRCULATION. "To validate the function of GM18840, Meg3, Dnm3os, and Pvt1 in MIRI, we carried out RNA-seq analysis in an in vitro model of simulated ischemia." (PMID 34322480, 2021).
joint disorders (1 paper, 2021). "However, our results, which highlighted the value of lnc-PVT1 and miR-146a as biomarkers for RA and OA, could be a beginning for more studies on a wider scale to understand the exact role of these biomarkers in joint disorders and the ability to use them as a therapeutic target." (PMID 34947913, 2021).
liver disorder (1 paper, 2017). A disease involving the liver. "In this study, Pvt1 was down regulated both in macrophage and liver, the value of log2 folded change in macrophage was −6.0, much lower than that in liver (−2.8), such significant expression difference indicated an important role of macrophage in inhibiting liver disorders." (PMID 29383134, 2017).
low grade glioma (1 paper, 2022). A grade I or grade II glioma arising from the central nervous system. "Gene expression-based survival analysis showed that six from seven detected highly m6A modified lncRNAs (PVT1, SLCO4A1, HRAT92, AGAP2-AS1, CEROX1 and ENSG00000262223 had an impact on the prognosis of low-grade glioma (LGG) and GBM (FDR adj." (PMID 35361860, 2022).
Lymphatic Metastasis (1 paper, 2023). Transfer of a neoplasm from its primary site to lymph nodes or to distant parts of the body by way of the lymphatic system. "Patients with high PVT1 expression had worse prognosis, a later FIGO stage, and were associated with lymphatic metastasis and LVSI." (PMID 36869031, 2023).
monoclonal gammopathy of undetermined significance (1 paper, 2020). "We examined PVT1/MYC expression using real-time PCR in plasma cells purified from 59 monoclonal gammopathy of undetermined significance (MGUS) and 140 MM patients." (PMID 32992461, 2020).
muscle atrophy (1 paper, 2025). The loss of muscle tissue due to inactivity or disease. "In addition, H19, HOTAIR, MALAT1 and PVT1 are highly expressed in the kidneys of CKD patients and are associated with muscle atrophy but do not directly mediate the pathogenesis of muscle atrophy in CKD patients." (PMID 40034097, 2025).
myelodysplastic syndrome (1 paper, 2023). A clonal hematopoietic disorder characterized by dysplasia and ineffective hematopoiesis in one or more of the hematopoietic cell lines. "The lncRNAs LOC101928834, H19, WT1-AS, TCL6, LEF1-AS1, EPB41L4A-AS1, PVT1, GAS5 and ZFAS were found to be relevant to myelodysplastic syndrome (MDS) pathogenesis and outcome." (PMID 36607351, 2023).
Nephroblastoma (1 paper, 2020). An embryonal neoplasm characterized by the presence of epithelial, mesenchymal, and blastema components. "Using MCODE in Cytoscape, 4 key genes (PVT1, hsa-mir-187, hsa-mir-551a, and LINC00484), which may play an important role in the development of nephroblastoma, were found to be densely connected." (PMID 32149111, 2020).
oral cancer (1 paper, 2024). "Several studies have revealed that PVT1 promoted the progression of oral cancer by serving as a ceRNA to target the miR‐375/YAP121 or miR‐150‐5p/GLUT‐147 axes." (PMID 39320020, 2024).
ovarian serous cystadenocarcinoma (1 paper, 2025). A malignant serous cystic epithelial neoplasm arising from the ovary. "Scatter plots show the correlations between FAM171A2 mRNA expression and six lncRNAs (BACE1-AS, GAS5, HOTAIR, HOXA10-AS, PVT1, and UCA1) in ovarian serous cystadenocarcinoma samples (n = 379) from the ENCORI database." (PMID 41303609, 2025).
parathyroid tumors (1 paper, 2022). "The deregulated expression of specific lncRNAs (lncRNA PVT1, lncRNA GLIS2-SA1, and lncRNA BC200) also appears to characterize molecular signatures of human PCs, distinguishing between benign and malignant parathyroid tumors." (PMID 35282432, 2022).
prediabetes (1 paper, 2022). "Therefore, based on the results of present study, we suggested that lncRNAs TCONS_00334653 and PVT1 might be the potential therapeutic or diagnostic target for the treatment of prediabetes with HTG." (PMID 35501901, 2022). "Therefore, downregulated PVT1 could also cause to damage in some extent and it might play a role for the lipid metabolism in the prediabetes." (PMID 35501901, 2022). "The TCONS_00334653 and PVT1 were detected the key lncRNAs for the prediabetes with HTG, which might be a potential therapeutic or diagnostic target for the treatment of prediabetes with HTG." (PMID 35501901, 2022). "However, our study found out PVT1 was downregulating in the prediabetes with HTG, it might be consistent with that overexpressed MYC is vulnerability to the inhibition of lipogenesis." (PMID 35501901, 2022). "Therefore, the TCONS_00334653 and PVT1 were detected the key lncRNAs for the prediabetes with HTG, which might be a potential therapeutic or diagnostic target for the treatment of prediabetes with HTG according to the results of validation in the GEO database, qRT-PCR and ROC curves." (PMID 35501901, 2022). "We found out that the TCONS_00334653 and PVT1, whose target mRNA are MYC and HIST1H2BM, were downregulating in the prediabetes with HTG." (PMID 35501901, 2022). "These curves and corresponding AUCs showed that lncRNAs PVT1 and TCONS_00334653 as biomarkers have diagnosed ability to discriminate HTG from NTG in the prediabetes patients." (PMID 35501901, 2022). "There were significant difference between prediabetes with HTG and NTG, both of PVT1 (z = 40.400, P < 0.001) and TCONS_00334653 (z = 5.757, P = 0.016)." (PMID 35501901, 2022).
pregnancy diseases (1 paper, 2021). "Thus, PVT1, considered to be an important oncogene, may also be a critical lncRNA regulator in placenta physiology and therefore pregnancy diseases." (PMID 33923632, 2021).
prostate (1 paper, 2020). "For example, the DE-lncRNAs PVT1, PCAT1, and PCAT10/CTBP1-AS have been previously studied and implicated in prostate tumorigenesis." (PMID 32059012, 2020).
psoriasis vulgaris (1 paper, 2023). Plaque psoriasis is the most common presentation of psoriasis. "In SLE and psoriasis vulgaris (PV), low levels of PVT1 have been linked to immune system dysfunction." (PMID 36980827, 2023).
pulmonary fibrosis (1 paper, 2023). Chronic progressive interstitial lung disorder characterized by the replacement of the lung tissue by connective tissue, leading to progressive dyspnea, respiratory failure, or right heart failure. "The expression of lncRNA PVT1 can be enhanced by FOXM1, a profibrotic factor, leading to excessive pulmonary fibrosis." (PMID 37367427, 2023).
renal tumors (1 paper, 2021). "Common dysregulation in renal tumors outlines the essential role of PVT1 in the development of RCC." (PMID 33947142, 2021).